TRAF6 (TNF receptor associated factor 6)
Diseases named in the same sentence as TRAF6 in open-access papers (continued):
Sharing a sentence is not in itself a finding about the gene and the disease.
Sepsis (continued). "Moreover, the expression levels of IRAK1, TRAF6, and miR-146a were also determined in the severe sepsis and healthy subjects to analyze whether these polymorphisms are associated with the expression levels of these cytokines." (PMID 24701036, 2014). "Tumour necrosis factor receptor-associated factor 6 (TRAF6) functions downstream of TLR4-induced inflammatory pathways as a primary adaptor, leading to multiorgan failure in individuals with sepsis." (PMID 40624022, 2025). "Previous studies have shown that miR-125b suppresses NF-κB activation through direct targeting of TRAF6 in sepsis and promotes inflammation via A20 inhibition in rheumatoid arthritis." (PMID 41471849, 2025). "miR-23b improved sepsis-induced cardiomyopathy by attenuating the inflammatory response, suppressing apoptosis, and preventing NF-κB activation via targeted inhibition of TRAF6 and IκκB." (PMID 40041174, 2025). "In conclusion, CYLD alleviated sepsis-induced inflammation by interacting with the TRAF6/sNASP axis." (PMID 40108019, 2025). "Further analysis of the correlation between TRAF6 and miR‐126‐5p in patients with sepsis‐induced ALI unraveled that miR‐126‐5p was negatively correlated with TRAF6 in patients with sepsis‐induced ALI." (PMID 37248197, 2023). "For disclosing the regulatory mechanism of PMS in sepsis-induced organ damage, functions of the TRAF6/NF-κB pathway in this process were studied." (PMID 37288729, 2023). "TRAF6 expression in patients with sepsis‐induced ALI was higher than that in patients with sepsis without ALI." (PMID 37248197, 2023). "Given TRAF6’s essential role in macroautophagy/autophagy activation triggered by TLR4 signaling, and the established connection between autophagy and sepsis-induced cardiomyopathy, we proceeded to treat LPS-induced BMDMs with si-TRAF6." (PMID 37919806, 2023). "In this research, we noticed that PMS treatment significantly reduced TRAF6 and p-NF-κB protein levels in the lung, liver and heart tissues of the sepsis mouse model." (PMID 37288729, 2023). "The consequences indicated that the TRAF6/NF-κB pathway influenced the protective effect of PMS in sepsis-triggered apoptosis and inflammation." (PMID 37288729, 2023). "The effects of the TRAF6/NF-κB pathway on PMS regulation of sepsis-induced apoptosis and inflammation were further explored." (PMID 37288729, 2023). "Taken together, the present research indicated that PMS relieved sepsis-triggered organ dysfunction and inflammation, which was modulated by the TRAF6/NF-κB pathway." (PMID 37288729, 2023). "In Sufu-cKO mice, we demonstrated that TRAF6 expression was required for sepsis-induced lung inflammation." (PMID 37441604, 2023). "Initially, we conducted an analysis of the microarray GSE145227 in the context of sepsis, identifying potential lncRNAs that bind to TRAF6." (PMID 37919806, 2023). "Our study discovered an anti-inflammatory role of Sufu in sepsis-induced lung inflammatory response and identifies the Sufu-TRAF6 axis as a potential therapeutic target for the treatment of sepsis." (PMID 37441604, 2023). "TRAF6 is a central regulator of sepsis, and blocking CD40–TRAF6 pathway while leaving CD40–TRAF 2, 3, 5 pathways functional would cause less severe immune-suppressive side effects." (PMID 36303116, 2022). "LncRNA MIAT promotes inflammation and oxidative stress in sepsis-induced cardiac injury through the miR-330-5p/TRAF6/NF-κB axis." (PMID 36091044, 2022). "Similar to this study, we found that the activation of TRAF6 or induction of NF-κB reduced the effects of Pellino1 on inflammation in vitro model of sepsis." (PMID 33632252, 2021). "It was found that sepsis induced significant promotion of TRAF6 in the heart, and Deh mitigated TRAF6 upregulation in sepsis mice." (PMID 34489703, 2021).
Sepsis (continued). "In conclusion, Deh restrains sepsis-induced cardiomyocyte injury by inhibiting the TRAF6/NF-κB pathway." (PMID 34489703, 2021). "The activation of TRAF6 or induction of NF-κB attenuated the effects of Pellino1 on inflammation in in vitro model of sepsis." (PMID 33632252, 2021). "We demonstrated that Pellino1 mRNA and protein expressions were increase in lung tissue of lung injury of sepsis and enhanced lung injury in sepsis mice by induction TRAF6/ NF-κB signaling." (PMID 33632252, 2021). "The inhibition of TRAF6 or suppression of NF-κB reduced the effects of Pellino1 on inflammation in in vitro model of sepsis." (PMID 33632252, 2021). "The inhibition of TRAF6 or suppression of NF-κB reduced the effects of Pellino1 on inflammation in vitro model of sepsis." (PMID 33632252, 2021). "It was revealed that TRAF6, p-NF-κB (in the whole cell) and nucleus p-NF-κB were upregulated in both sepsis mouse myocardial tissues and LPS-induced H9C2 cells." (PMID 34489703, 2021). "The present study revealed that sepsis promoted TRAF6 expression and the nucleus translocation of phosphorylated NF-κB p65." (PMID 34489703, 2021). "TRAF6 inhibitor attenuated the effects of Pellino1 on inflammation and lung injury in mice of sepsis." (PMID 33632252, 2021). "Second, miR-146a protects cardiomyocytes from sepsis-induced cell dysfunction via inhibition of NF-κB activity by targeting TRAF6 and IRAK1." (PMID 30224945, 2018). "For example, Nur77 functions as a negative regulator of TLR-IL-1R signaling via interaction with TRAF6 in the cytoplasm to protect against the development of inflammatory bowel disease and sepsis." (PMID 28977843, 2017). "Our study demonstrated that severe sepsis patients expressed lower levels of miR-146a and higher levels of TRAF-6 and IRAK-1 than the healthy controls." (PMID 24701036, 2014). "In total, 37 patients with severe sepsis and 40 healthy individuals were stochastically chosen to investigate the expression levels of miR-146a, TRAF-6, and IRAK-1 in PBMCs." (PMID 24701036, 2014). "Nevertheless, our results confirmed that the expression level of miR-146a was significantly lower in severe sepsis patients and was accompanied by higher expression levels of TRAF-6 and IRAK-1 compared to the healthy controls." (PMID 24701036, 2014). "PMS suppressed sepsis-induced organ dysfunction by regulating the TRAF6/NF-κB axis, and PMS treatment may be considered as a novel strategy for sepsis-caused damage in future." (PMID 37288729, 2023). "Interestingly, TRAF6 overexpression reversed the functions of PMS in sepsis-mediated organ damage, apoptosis and inflammation." (PMID 37288729, 2023). "Knockdown of TRAF6 also resulted in decreased mRNA expression of Tnfα and Il-6 in Sufu-cKO mice induced with LPS, suggesting that Sufu suppressed lung inflammation during sepsis via interfering TRAF6 function." (PMID 37441604, 2023). "Inhibiting TRAF6 has been demonstrated to mitigate sepsis-induced cardiomyopathy." (PMID 37919806, 2023). "In this study, we investigated the interplay between sepsis and Hh signaling, and uncovered a novel functional mechanism of TRAF6: that TRAF6 undergoes phase separation for signaling in LPS-induced innate immunity, which is essential for subsequent autoubiquitination and NF-κB activation." (PMID 37441604, 2023). "We further examined TRAF6 expression in patients with sepsis‐induced ALI utilizing RT‐qPCR and the findings suggested that plasma TRAF6 expression levels in patients with sepsis‐induced ALI were elevated compared with those in patients with sepsis without ALI (p < 0.05)." (PMID 37248197, 2023). "This beneficial function of PMS in sepsis was mediated by the TRAF6/NF-κB pathway." (PMID 37288729, 2023). "Furthermore, we found that Pellino1 triggered TRAF6/ NF-κB signaling and enhanced inflammation in lung injury of sepsis." (PMID 33632252, 2021).
Sepsis (continued). "Collectively, these results suggest that Pellino1 may be an important regulator of inflammation in lung injury of sepsis by TRAF6/ NF-κB signaling." (PMID 33632252, 2021). "Our work indicates that Nur77 deficiency in mice increased their susceptibility to LPS-induced sepsis and acute liver injury, and reveal a critical mechanism wherein Nur77 interacts with TRAF6 and regulate its auto-ubiquitination in in vivo mouse model of sepsis." (PMID 26839514, 2016). "These in vivo observations reveals an important protective role for Nur77 in LPS-induced sepsis through its regulation to TRAF6 signalling, and highlights the potential clinical application of Nur77 as a molecular target in prevention and/or treatment of sepsis." (PMID 26839514, 2016). "Although several variants in the TLR signaling pathway genes were implicated in susceptibility to ALI and sepsis, the effect of variation in TRAF6 on human diseases susceptibility was not reported till now." (PMID 22901274, 2012). "Moreover, the rs2910164 and rs57095329 SNPs could functionally affect the miR-146a expression levels and the miR-146a could negatively regulate the expression of IRAK1 and TRAF6 in severe sepsis patients." (PMID 24701036, 2014). "Animal studies also indicated that inhibition of TRAF6 in dominant-negative sNASP mutant mice and a PP4-overexpressing mice model both improved symptoms and systemic inflammation of sepsis-induced ALI." (PMID 40108019, 2025). "TIGAR elicits a complex formation with TAK1 and TRAF6 through protein–protein interaction and activation of TAK1, thereby promoting inflammation and accelerating the progression of sepsis." (PMID 38773142, 2024). "In summary, this study provides evidence that SLAMF7 is an important negative regulator of sepsis-induced inflammation and reveals that SLAMF7 cooperates with SHIP1 to inhibit TRAF6 ubiquitination and suppress proinflammatory cytokine production." (PMID 36749634, 2023). "To further address whether TRAF6 expression was required and sufficient for sepsis-induced lung inflammation in Sufu-cKO mice, we designed a TRAF6-specific small interfering RNA (siRNA) and transfected Sufu-cKO mice by liposome incorporation to knockdown endogenous TRAF6 expression." (PMID 37441604, 2023). "Pellino1−/− mice suppressed the protein expression of Pellino1, TRAF6 and NF-κB and inhibited the levels of TNF-α, IL-6, IL-1β and IL-18 in mice of sepsis." (PMID 33632252, 2021). "Our research team has shown that corilagin exerts an anti-inflammatory effect in sepsis through downregulation of expression of TLR4, MyD88, TRIF, and TRAF6 in the TLR4 signaling pathway." (PMID 32849545, 2020). "We also found that in comparison to the untreated sepsis group, narciclasine treatment reduced the protein expression of MyD88, IRAK-1 and TRAF-6 in the livers of septic neonatal rats." (PMID 32076015, 2020). "The DE miRNAs (miR-1246, miR-200, miR-223, miR-29b, and miR-145) reported earlier in sepsis patients, for example, contribute to regulation of signaling molecules (IKKα, MAL, TRAF6, MyD88) in the TLR-4 pathway during LPS exposure." (PMID 33113825, 2020). "Mechanistically, we observed that Nur77 can interact with TRAF6, a crucial adaptor molecule in the Toll-like receptor-interleukin 1 receptor (TLR-IL-1R) signalling pathway, in in vivo mouse model of sepsis." (PMID 26839514, 2016). "The relative expression levels of TRAF-6 and IRAK-1 were significantly higher in patients with severe sepsis compared to those of the healthy controls (P < 0.0001 and P = 0.0078, resp)." (PMID 24701036, 2014). "Our study showed similar results; the downregulation of miR-146a expression was accompanied by the upregulation of TRAF-6 and IRAK-1 in severe sepsis patients." (PMID 24701036, 2014). "Our results support this view and show that deregulated miR-146a negatively regulated its target molecules TRAF-6 and IRAK-1 in severe sepsis patients." (PMID 24701036, 2014).
Sepsis (continued). "miR-146a attenuates sepsis-induced cardiac dysfunction by preventing NF-κB activation, inflammatory cell infiltration, and inflammatory cytokine production via targeting of IRAK and TRAF6 in both cardiomyocytes and inflammatory monocytic cells." (PMID 40041174, 2025). "Their result suggested that miR-146a might have a protective effect on sepsis-induced cardiac dysfunction by targeting IRAK and TRAF6." (PMID 38792088, 2024). "Our study sheds light on the regulatory role of SLAMF7 in sepsis and uncovers the interaction between SLAMF7 and TRAF6/SHIP1 to transmit downstream signals, which may provide support for the development of therapeutic strategies for sepsis." (PMID 36749634, 2023). "Furthermore, PMS lowered TRAF6 and p-NF-κB p65 levels, whereas TRAF6 overexpression reversed the protective influences of PMS in organ injury, apoptosis and inflammation triggered by sepsis." (PMID 37288729, 2023). "We have tested the expression of TRAF6 in patients with sepsis‐induced ALI, and the results were as speculated: TRAF6 expression was elevated in sepsis‐induced ALI." (PMID 37248197, 2023). "In this study, miR‐126‐5p was reduced in sepsis‐induced ALI, and it was speculated that the target gene TRAF6 would be elevated in sepsis‐induced ALI." (PMID 37248197, 2023). "Next, we found that Pellino1 protein could induced the protein expression of Pellino1, TRAF6 and NF-κB and increased the levels of TNF-α, IL-6, IL-1β and IL-18 in mice of sepsis." (PMID 33632252, 2021). "In addition, miR-146, which is strongly reduced in sepsis, is well known for its anti-inflammatory properties by negatively regulating NF-kB activities and by directly targeting IRAK-1 and TRAF6." (PMID 33362557, 2020). "Therefore, examining the function and mechanism of TLR4/TRAF6 in LPS-induced myocardial injury is expected to reveal a novel therapeutic approach for sepsis-induced myocardial injury." (PMID 34489703, 2021). "Corilagin showed the capability in down-regulating TRAF6 and TRIF signaling pathway in extreme inflammation status, which demonstrated that Corialgin might have the potential to control outbreak of inflammatory cascade in sepsis." (PMID 28056977, 2017). "Since the main signaling action of macrophage IPMK appears to rely on its non-catalytic role in controlling TRAF6, developing ways to selectively deplete macrophage IPMK levels could be useful to manage uncontrolled inflammatory response, such as sepsis." (PMID 36830701, 2023).
viral infection (42 papers, 2009 to 2025). "Overexpression of miR-146a promotes viral gene replication following viral infection by targeting TNFR-associated factor 6 (TRAF6)." (PMID 38753689, 2024). "Based on our results, we propose a model that preexposure of a host to viral infections results in an increased expression of K63-linked polyubiquitinated proteins and TRAF6 K63-linked ubiquitination." (PMID 29515583, 2018). "The deubiquitinases OTUB1/2, UCHL1, MYSM1 and DUBA inhibit K63-linked ubiquitination of TRAF3 or TRAF6 and negatively regulate IFNs production during viral infection." (PMID 29734366, 2018). "In contrast, upon viral infection, the recruitment of TRAF6 and TBK1 to VISA was enhanced in GPATCH3 deficient cells." (PMID 28414768, 2017). "The role of the TRAF family member TRAF6 has been previously implicated to be necessary for full NF-κB activation in response to viral infection and cytosolic RNA." (PMID 20161788, 2010). "Similarly, it has been reported that some deubiquitinases including OTUB1/2, UCHL1, MYSM1 and DUBA can remove K63-linked ubiquitination of either TRAF3 or TRAF6, thus inhibiting IFNs production during viral infection." (PMID 29734366, 2018). "The exploration of the TRAF family, particularly TRAF5 and TRAF6, has garnered significant attention within immunological research, especially in the context of viral infections and vaccination responses." (PMID 40136419, 2025). "Together, TRAF5 and TRAF6 serve as critical links between platelet activation and systemic immune dysregulation during viral infections." (PMID 40136419, 2025). "In the case of viral infection, Lgals3bp forms complex with Traf6 or Traf3, and subsequently recruits TAK1 and TBK1, which then signal the translocation of the transcription factors NF-κB, IRF3, and IRF7 from the cytoplasm to the nucleus." (PMID 38279161, 2024). "During viral infection, the RNA helicase DDX46 binds more strongly to transcripts, which encode MAVS, TRAF3, and TRAF6, and other antiviral protein, resulting in the recruitment of ALKBH5 to demethylate these transcripts." (PMID 36176733, 2022). "BST2 has also been reported to have a pro-inflammatory function through the Syk/TRAF2/TRAF6/TAK1/NF-κB pathway under conditions of viral infection." (PMID 35316682, 2022). "For instance, OTUD1 increases Smurf1 expression levels to promote degradation of the MAVS/TRAF3/TRAF6 signalosome and inhibit the innate immune response to viral infection." (PMID 35280681, 2022). "As TRAF6 stability is regulated in response to many external cues including virus infections, micro RNAs and inflammation, it was interesting to compare the protein stabilities of the different TRAF6 forms." (PMID 34298830, 2021). "GPATCH3 binding to MAVS prevents the assembly of the MAVS/TRAF6/TBK1 complex during viral infection." (PMID 32536927, 2020). "Because TRAF6 is involved in apoptosis after viral infection, NLRP11 can potentially inhibit apoptosis, which also ensures the survival of the host cells." (PMID 32536927, 2020). "Despite TRAF6 playing an important role in regulating host immunity and viral infection, the deubiquitination of TRAF6 induced by viral infection remains elusive." (PMID 30194441, 2018). "Here, our findings uncover the phenomenon of MAVS/TRAF3/TRAF6 downregulation at the early stage of viral infection, and partially clarify the mechanisms of the dynamics of downregulation of the signalosome and IFNs induction." (PMID 29734366, 2018). "For example, USP25 was reported to be able to enhance the stability of TRAF3 and TRAF6, thus promoting IFNs induction by viral infection." (PMID 29734366, 2018). "TRAF6 is an E3 ubiquitin ligase that is critical for type I interferon responses to viral infection." (PMID 28380049, 2017). "We found that TBK1 and IKKε were recruited to MAVS only in TRAF6-expressing cells upon viral infection." (PMID 29125880, 2017).